CCT2 (chaperonin containing TCP1 subunit 2)
Description:
Component of the chaperonin-containing T-complex (TRiC), a molecular chaperone complex that assists the folding of actin, tubulin and other proteins upon ATP hydrolysis. The TRiC complex mediates the folding of WRAP53/TCAB1, thereby regulating telomere maintenance. As part of the TRiC complex may play a role in the assembly of BBSome, a complex involved in ciliogenesis regulating transports vesicles to the cilia.
Synonyms: TCP-1-beta; 99D8.1; CCTB; CCT-beta; HEL-S-100n; PRO1633
Tractability: Small molecule: a structure with a bound ligand is known. Antibody: its Gene Ontology location is reachable by antibodies, with high confidence. PROTAC: UniProt records ubiquitination sites on it; ubiquitination databases record sites on it; its protein half-life has been measured.
Target class: Enzyme; Hydrolase
Gene: Protein-coding gene on chromosome 12 (69,585,423 to 69,601,577, forward strand). Ensembl gene ENSG00000166226.
Subcellular location: Cytoplasm
Subcellular location (Human Protein Atlas): Cytosol; Connecting piece; Mid piece; Principal piece
Pathways (Reactome):
Metabolism of proteins: Association of TriC/CCT with target proteins during biosynthesis; Cooperation of PDCL (PhLP1) and TRiC/CCT in G-protein beta folding; Folding of actin by CCT/TriC; Formation of tubulin folding intermediates by CCT/TriC; Prefoldin mediated transfer of substrate to CCT/TriC
Signal Transduction: RHOBTB1 GTPase cycle; RHOBTB2 GTPase cycle
Immune System: Neutrophil degranulation
Organelle biogenesis and maintenance: BBSome-mediated cargo-targeting to cilium
Gene Ontology:
Molecular function: protein binding; protein folding chaperone; ubiquitin protein ligase binding; ATP binding; ATP hydrolysis activity; ATP-dependent protein folding chaperone
Biological process: chaperone-mediated protein complex assembly; positive regulation of protein localization to Cajal body; positive regulation of telomerase RNA localization to Cajal body; positive regulation of telomere maintenance via telomerase; protein folding; protein stabilization; scaRNA localization to Cajal body
Cellular component: chaperonin-containing T-complex; cytoplasm; cytosol; extracellular exosome; microtubule; azurophil granule lumen; extracellular region; cell body; zona pellucida receptor complex
Genetic constraint (gnomAD): Loss-of-function variants: 10 observed, 38.1 expected, observed/expected ratio (o/e) 0.26, 90% interval 0.16 to 0.44. The upper end of that interval is the gene's LOEUF score, 0.44, which puts it in group 1 of 6, group 1 being the genes least tolerant of losing a copy. Missense variants: 433 observed, 511.83 expected, observed/expected ratio (o/e) 0.85, 90% interval 0.78 to 0.92. Synonymous variants: 195 observed, 174.15 expected, observed/expected ratio (o/e) 1.12, 90% interval 1 to 1.26.
Homologues: Orthologues: chimpanzee CCT2 (100% identical), macaque CCT2 (100% identical), pig CCT2 (99% identical), rabbit CCT2 (99% identical), mouse Cct2 (98% identical), rat Cct2 (98% identical), guinea pig CCT2 (96% identical), tropical clawed frog cct2 (80% identical), Drosophila melanogaster CCT2 (71% identical), Caenorhabditis elegans cct-2 (66% identical), zebrafish cct2 (47% identical), zebrafish cct2 (18% identical). Paralogues in human: TCP1 (34% identical), CCT7 (33% identical), CCT5 (32% identical), CCT4 (31% identical), CCT3 (29% identical), CCT8 (26% identical), PIKFYVE (26% identical), CCT6A (25% identical), CCT6B (24% identical), CCT8L2 (24% identical), HSPD1 (21% identical), MKKS (18% identical), and 1 more.
Diseases named in the same sentence as CCT2 in open-access papers:
CCT2 is named in the same sentence as 98 diseases in open-access papers, as found by Europe PMC text mining. Sharing a sentence is not in itself a finding about the gene and the disease. The quoted sentences say what the papers report.
breast carcinoma (24 papers, 2017 to 2025). "Our findings revealed a significant association between high CCT2 expression and adverse outcomes in breast cancer patients." (PMID 39079960, 2024). "In this study, analysis of TCGA and GEO datasets revealed a significant increase in CCT2 expression in breast cancer tissues, which was associated with poor prognosis in breast cancer patients." (PMID 39079960, 2024). "We subsequently investigated the mechanisms underlying the CCT2-mediated promotion of breast cancer progression." (PMID 39079960, 2024). "Our study provides new insights into the molecular mechanisms underlying breast cancer progression, suggesting that CCT2 is a promising therapeutic target and prognostic predictor for breast cancer." (PMID 39079960, 2024). "In summary, these findings collectively demonstrate that CCT2 expression is elevated in breast cancer and is associated with poor prognosis." (PMID 39079960, 2024). "It is worth noting that we had achieved comparable results with the same CCT2-shRNA in breast cancer cells, in which 50% depletion of CCT2 resulted in ~40% loss of cell viability." (PMID 36185250, 2022). "Survival analysis suggested that CCT2 overexpression was independently associated with worse prognosis of patients with breast cancer, especially in luminal A subtype." (PMID 33869000, 2021). "Our previous published work showed that CT20p is selectively cytotoxic to breast cancer cells, and that modulating the levels of CCT2 by inhibition or overexpression regulated the susceptibility of cells to killing by CT20p." (PMID 29299146, 2017). "In the TCGA breast cancer dataset, CCT2 amplification and/or overexpression was associated with worse outcome, in agreement with studies in gall bladder carcinoma and with our current findings in NSCLC." (PMID 29112949, 2017). "Since our previous studies showed that the CCT2 subunit was essential for breast cancer growth and tumor formation, we first examined whether alterations of the CCT2 gene associated with cell cycle gene alterations." (PMID 33996588, 2021). "Previously, we established that 25-50% depletion of CCT2 caused loss of viability in MDA-MB-231 breast cancer cells and could inhibit tumor growth in a syngeneic mouse model of E0771 TNBC cells." (PMID 33996588, 2021). "To augment this data, we specifically examined the role of CCT2 in cell cycle progression using 2D and 3D cultures to investigate cellular and molecular changes directly associated with overexpressing the CCT2 subunit in luminal A cells, the most common subtype of breast cancer." (PMID 33996588, 2021). "To evaluate the impact of CCT2 on the metastatic potential of breast cancer cells, we conducted transwell and wound-healing assays." (PMID 39079960, 2024). "We then exposed CD4+ T cells to culture medium (CM) from CCT2-knockdown or CCT2-overexpressing breast cancer cells to compare their ability to modulate the T-cell response." (PMID 39079960, 2024). "The tumors in the shCCT2 group were significantly smaller and lighter in volume than those in the shNC group were, indicating that the knockdown of CCT2 in breast cancer cells delayed tumor growth in vivo." (PMID 39079960, 2024). "We further investigated the function and regulatory mechanism of CCT2 in the TME of breast cancer using a tumor-bearing model." (PMID 39079960, 2024). "Taken together, our findings demonstrate that CCT2 promotes oncogenic behavior in breast cancer cells." (PMID 39079960, 2024). "In our study, we observed that CCT2 silencing in breast cancer cells led to enhanced activation (CD40L) and the proinflammatory cytokine (IFN-γ and TNFα) production in CD4+ T cells within the tumor microenvironment." (PMID 39079960, 2024). "In breast cancer, knockdown of CCT2 was found to decrease the metastasis rate by preventing β‐catenin from entering the nucleus." (PMID 38363102, 2024).
breast carcinoma (continued). "Knockdown of CCT2 was found to decrease the metastasis rate of breast cancer cells by inhibiting the activity and expression of MMP2/9, which act as matrix metalloproteases to degrade the extracellular matrix." (PMID 38363102, 2024). "In conclusion, our research elucidates the critical function of CCT2 in breast cancer progression, primarily via the initiation of the JAK2/STAT3 signaling cascade." (PMID 39079960, 2024). "Together, these results suggest that CCT2 in breast cancer cells-derived exosomes modulate CD4+ T cells activation through the Ca2+-NFAT1 pathway, ultimately compromising antitumor immunity." (PMID 39079960, 2024). "Functional analysis revealed that CCT2 promoted breast cancer growth and metastasis through activation of the JAK2/STAT3 signaling pathway." (PMID 39079960, 2024). "We used a variety of datasets and a dedicated cohort, which included tissues from our cohort and more evidence of higher CCT2 expression in breast cancer tissues, to confirm our findings." (PMID 39079960, 2024). "Subsequent findings revealed the role of CCT2 in fostering breast cancer proliferation, migration, and invasion, highlighting its importance in cancer progression." (PMID 39079960, 2024). "Univariate and multivariate Cox regression analyses confirmed that >3 LN metastases and CCT2 expression were independent prognostic indicators for overall survival in patients with breast cancer." (PMID 39079960, 2024). "We subsequently assessed CCT2 expression in a cohort of human breast cancer tissues obtained from Qilu Hospital, alongside normal tissues." (PMID 39079960, 2024). "To further substantiate the oncogenic role of CCT2 in breast cancer, we investigated its biological functions by transfecting breast cancer cells with CCT2 overexpression plasmids and siRNAs." (PMID 39079960, 2024). "These insights into the function and mechanism of CCT2 highlight its potential as a therapeutic target for breast cancer." (PMID 39079960, 2024). "Our analysis revealed that, compared with normal tissues, breast cancer tissues presented greater CCT2 mRNA expression." (PMID 39079960, 2024). "Our investigation revealed the presence of CCT2 in breast cancer cell-derived exosomes, which contributed to the suppression of CD4+ T cells activation and proinflammatory cytokine secretion." (PMID 39079960, 2024). "Most interestingly, we discovered that exosomal CCT2 derived from breast cancer cells suppressed the activation and proinflammatory cytokine secretion of CD4+ T cell." (PMID 39079960, 2024). "Taken together, the results demonstrate that breast cancer cell exos-derived CCT2 inhibits CD4+ T cells activation by limiting CD40L expression via the Ca2+-NFAT1 signaling pathway." (PMID 39079960, 2024). "Further evaluation of the clinical significance of CCT2 expression was conducted on the basis of the clinicopathological characteristics of breast cancer patients, with a focus on OS." (PMID 39079960, 2024). "To include cells in our study that also had mesenchymal markers, we used breast cancer cell lines in which we had previously evaluated CCT2 levels and then determined their expression of epithelial and mesenchymal markers." (PMID 35749519, 2022). "Overexpression of CCT2 increased the proliferation and invasiveness of breast epithelial cells and promoted spheroid and anchorage-independent growth of luminal A breast cancer cells, correlating with increased MYC and CCND1 expression." (PMID 36185250, 2022). "Cells from both SCLC cell lines showed positive CCT2 staining with similar trends to what was seen in breast cancer." (PMID 35749519, 2022). "Using a clinically validated method for capturing CTCs, we evaluated detection of intracellular CCT2 staining for visualization of breast cancer and small cell lung (SCLC) cancer cells." (PMID 35749519, 2022).
breast carcinoma (continued). "SK-N-AS and IMR-32 cells were transfected with a lentiviral vector (LVV) to exogenously express a FLAG-tagged CCT2 construct (CCT2-FLAG) that we previously used in breast cancer cells." (PMID 36185250, 2022). "Guestet al. identified that TCP1 together with CCT2 (TRiC subunit) are commonly altered in breast cancer and essential for the proliferation of breast cancer cells." (PMID 36239351, 2022). "Overexpressing CCT2 in luminal breast cancer cells increased cell proliferation, spheroid growth, and anchorage-independent growth, while CCT2 depletion prevented tumor growth in a syngeneic model of triple-negative breast cancer (TNBC)." (PMID 35749519, 2022). "T47D cells, representative of early-stage luminal A breast cancer, have lower protein levels of CCT2 compared to TNBC cells, like MDA-MB-231." (PMID 35749519, 2022). "We previously showed in breast cancer cells expressing CCT2-FLAG that ~70% of the CCT2-FLAG protein was incorporated into the CCT hetero-oligomeric complex and ~30% remained as an unincorporated monomer." (PMID 36185250, 2022). "Studies have shown that CCT2 expression negatively correlates with survival in breast cancer patients, which supports our results." (PMID 35372018, 2022). "Exogenously expressing CCT2 in early stage, luminal A breast cancer cells increased their proliferation and anchorage-independent growth." (PMID 36185250, 2022). "Utilizing 3D culture conditions, enabled through the use of ULA plates, we investigated the effect that CCT2-FLAG overexpression would have on spheroid formation by breast cancer cells." (PMID 33996588, 2021). "Showalter and colleagues found that CCT2 overexpression enhanced the proliferation and invasion capacities of breast cancer cells." (PMID 34676169, 2021). "Consistent with our results, CCT2 has been observed to be overexpressed and essential for the survival of various tumors, including liver, prostate, lung, and breast cancer." (PMID 34164393, 2021). "We found that expression of one of the CCT subunits, CCT2, inversely correlates with breast cancer patient survival and is subject to copy number alterations through genomic amplification." (PMID 33996588, 2021). "Particularly, the global expression of CCT2 in breast cancer tissues was higher than normal tissues." (PMID 33869000, 2021). "We explored the prognostic value of CCT2 expression using KM-plotter database containing a total of 6,243 breast cancer samples." (PMID 33869000, 2021). "Though all these previous studies laid emphasis on the significance of CCT2 in breast cancer, what they focused on was only the growth and survival of breast cancer cells." (PMID 33869000, 2021). "In breast cancer, CCT2 expression was significantly upregulated in HER2-positive (HER2+) group, and more malignant group." (PMID 33869000, 2021). "We also found CCT2 was an independent significant prognostic factor for breast cancer according to multivariate analysis of TCGA cohort after adjusting for age, AJCC stage, ER status, PR status, as well as HER2 status." (PMID 33869000, 2021). "Of the CCT subunits, we found that CCT2 expression inversely correlated with the overall survival of breast cancer patients." (PMID 33996588, 2021). "In support, we previously reported that breast cancer patients with CCT2 genetic alterations died up 70 months sooner than patients without alterations." (PMID 33996588, 2021). "They identified that CCT1 and CCT2 were necessary for growth/survival of breast cancer cells in vitro and were determinants of overall survival in breast cancer patients." (PMID 33869000, 2021). "The importance of CCT2 in breast cancer was further examined with patient data from The Cancer Genome Atlas (TCGA), showing that only genomic alterations in CCT2 resulted in statistically significant differences in patient survival." (PMID 31964905, 2020).
breast carcinoma (continued). "All of these, with the exception of TCP1, have also been linked to breast cancer, while FLNA, GSK3B and CCT2 are specifically linked to TNBC." (PMID 32127582, 2020). "We show this through a bioinformatics analysis of possible CCT interactors that are involved in cell cycling and whose expression co-occurs with CCT2 in breast cancer." (PMID 31964905, 2020). "To address this, we expressed CCT2 as well as silenced cct2 gene expression in epithelial and breast cancer cells." (PMID 31964905, 2020). "Our focus on CCT2 as a potential therapeutic target for inhibition of chaperonin activity initiated upon discovering correlations between CCT2 expression and reduced breast cancer patient survival." (PMID 31964905, 2020). "To this end, we investigated the activity of CCT2 (CCTβ) by overexpressing or depleting the subunit in breast epithelial and breast cancer cells." (PMID 31964905, 2020). "Increased CCT2 expression was sustained through all breast cancer stages and correlated with poor prognosis in patients." (PMID 31964905, 2020). "High expression of CCT2 occurred in liver, prostate and breast cancer and correlated with cancer severity and unfavorable prognosis." (PMID 31101846, 2019). "Collectively, these results suggest that high expression of HSPA2 and DNAJC20 is associated with low-risk breast cancer, whereas high expression of HSP90AA1, CCT1, CCT2 and CCT6A correlates with high-risk breast cancer." (PMID 31101846, 2019). "Another study reported that CCT1 and CCT2 were amplified in breast cancer and necessary for cell survival and growth." (PMID 31101846, 2019). "Herein, using The Cancer Genome Atlas and KM plotter database, we showed strong association between expression of at least six HSP-encoding genes (namely: HSPA2, DNAJC20, HSP90AA1, CCT1, CCT2 and CCT6A) and survival of breast cancer patients." (PMID 31101846, 2019). "Our previous studies with breast cancer revealed that the CCT2 subunit was overexpressed in tumor tissues as compared to normal tissues, was increased with advanced disease, and was inversely correlated with patient survival." (PMID 29299146, 2017). "Additionally, we investigated the possible mechanism by which CD4+ T cells activation was regulated by CCT2, which was derived from breast cancer cell exos." (PMID 39079960, 2024). "Additionally, we demonstrated that Trim21 modulates CCT2 ubiquitination and degradation, thereby influencing its impact on breast cancer progression." (PMID 39079960, 2024). "Moreover, CHX chase assays demonstrated that Trim21 overexpression promoted CCT2 protein degradation in breast cancer cells, whereas Trim21 knockdown extended the half-life of the CCT2 protein." (PMID 39079960, 2024). "Furthermore, compared with that in the control group, the expression of CCT2 in CD4+ T cells decreased following treatment with exos derived from CCT2-knockdown breast cancer cells, whereas CCT2-overexpressing exos had the opposite effect." (PMID 39079960, 2024). "Exosomes (Exos) were harvested from stable CCT2-knockdown or CCT2-overexpressing breast cancer cell culture medium via ultracentrifugation and characterized using nanoparticle tracking analysis (NTA), transmission electron microscopy (TEM) and western blot analysis." (PMID 39079960, 2024). "Moreover, we observed elevated mRNA expression levels of CCT2 in breast cancer tissues compared with their paired normal counterparts." (PMID 39079960, 2024). "Moreover, functional assays uncovered the crucial role of CCT2 in breast cancer progression via the JAK2/STAT3 signaling pathway." (PMID 39079960, 2024). "Furthermore, elevated levels of CCT2 were correlated with worse prognoses in breast cancer patients." (PMID 39079960, 2024). "Moreover, we revealed that CCT2 contributes to breast cancer immune evasion by packaging into breast cancer cell-derived exosomes, where it regulates CD4+ T cell activation through the Ca2+-NFAT1 pathway." (PMID 39079960, 2024).